NLGN2 (neuroligin 2)
Diseases named in the same sentence as NLGN2 in open-access papers (continued):
Sharing a sentence is not in itself a finding about the gene and the disease.
insulinoma (1 paper, 2013). "Neuroligin-2 is the predominant neuroligin isoform in islets and insulinoma cells." (PMID 23776533, 2013).
ischemic stroke (1 paper, 2025). A stroke disorder caused by obstruction of blood flow to the brain, due to thrombotic (local blood clot formation) or embolic (due to a blood clot or other material traveling from another site) event. "Single-gene GSEA revealed that the identified signature genes (Pip5k1c, Nlgn2, Fzd2, Cd86, Agpat1, and Degs2) converge on neuroinflammatory and apoptotic pathways critical in ischemic stroke pathogenesis." (PMID 40520774, 2025). "The results demonstrated that, in comparison to the control group, the expression of Pip5k1c, Nlgn2, Fzd2, Cd86, Agpat1, and Degs2 showed a downward trend with an increase in the onset time of ischemic stroke, and the decrease was most significant in the MCAO_12 h group (p < 0.01)." (PMID 40520774, 2025).
pancreatitis (1 paper, 2024). Inflammation of the pancreas. "This phenomenon could explain the heterogeneous pattern of NLGN2 localization in the normal human pancreas as being derived from the history of pancreatitis, therapeutic treatments, and individual exposome." (PMID 38413734, 2024). "Similarly, pancreatitis in caerulein-treated mice resulted in the mobilization of NLGN2 from the apical domain to the cytosol in acinar cells and ADM, and this relocalization was reversed after inflammatory injury cheased." (PMID 38413734, 2024). "In control Elast-K-Ras+/+ mice, caerulein-induced pancreatitis promoted intracellular localization of NLGN2 in acinar cells and ADM without reducing its expression level." (PMID 38413734, 2024).
renal fibrosis (1 paper, 2016). A final common manifestation of a wide variety of chronic kidney diseases characterized by glomerulosclerosis and tubulointerstitial fibrosis. "The list of genes includes Fblim1, Epha2, Wisp1, Parvg, Madcam1, Mybpc2, Cdh3, Gpr56, Troap, Pstpip1, Pcdh8, Nlgn2 and Mfap4, genes that based on Pubmed and Kidney and Urinary Pathway Knowledge Base12 searches have not been previously associated with renal fibrosis." (PMID 27189340, 2016).
viral encephalitis (1 paper, 2022). Encephalitis resulting from viral infection. "ELISA, enzyme‐linked immunosorbent assay; NFASC, neurofascin; NLGN2, neuroligin 2; NRXN3, neurexin 3; VE, viral encephalitis." (PMID 37786892, 2022).
virus infection (1 paper, 2022). "Pathogens directly damage axon tissue and participate in the process of virus infection, resulting in the destruction of NLGN2 protein." (PMID 37786892, 2022).
cancer (5 papers, 2018 to 2024). A tumor composed of atypical neoplastic, often pleomorphic cells that invade other tissues. "The inconsistency between the expression level and the expected prognosis in the other five genes (RHPN1-AS1, MELK, EIF5AL1, and G6PC3: upregulated, but HR < 1; NLGN2: downregulated, but HR > 1) may be attributed to a protective response mechanism in order to resist the development of cancer." (PMID 32953881, 2020). "In these cells, as well as in duodenal tuft cells, NLGN2 was coexpressed with doublecortin-like kinase 1 (DCLK1) (Fig. EV2C), an interactor of NLGN2 and a stemness marker in several cancers, including pancreatic preinvasive lesions, and in the gastrointestinal tract." (PMID 38413734, 2024).
psychiatric disorder (5 papers, 2017 to 2024). A disorder characterized by behavioral and/or psychological abnormalities, often accompanied by physical symptoms. "Moreover, NLGN2 has been associated with psychiatric disorders, but its implication in sleep remains underexplored." (PMID 30231918, 2018). "The study suggests that dysfunction of NLGN2 contributes to the pathogenesis of several psychiatric symptoms in patients with mental illnesses." (PMID 29230184, 2017). "Given that both Nlgn2 and the MDGA1 have been correlated with many psychiatric disorders, our data support the notion that cytosolic gephyrin aggregation may represent an interesting target for novel therapeutic strategies." (PMID 39284869, 2024). "A further detailed understanding of how Nlgn2 and MDGA1 differentially regulate gephyrin aggregation, and how these aggregates affect GABAergic synapse function, may therefore be relevant towards identifying pathophysiological mechanisms in Nlgn2- and MDGA1-related psychiatric disorders." (PMID 39284869, 2024).
neurodevelopmental disorder (4 papers, 2016 to 2025). A behavioral and cognitive disorder with onset during the developmental period that involves impaired or aberrant development of intellectual, motor, or social functions. "Nlgn2 (Neuroligin-2) is a gene associated with neurodevelopmental disorders." (PMID 40520774, 2025). "This is of relevance to help define the role of NLGN2 in SW generation during SWS as well as in sleep-related cognitive alterations observed in neurodevelopmental disorders." (PMID 38570872, 2024). "This work brings further insight into potential mechanisms of sleep duration and quality deregulation in neurodevelopmental disorders, notably involving NLGN2 and GABAergic neurotransmission." (PMID 38570872, 2024). "Neuroligin-2 (NLGN2), which mainly regulates gamma aminobutyric acid (GABA)ergic neurotransmission, but also cholinergic and dopaminergic transmission, was repeatedly associated with neurodevelopmental disorders." (PMID 38570872, 2024).
neurological disorders (2 papers, 2018 to 2025). "This highlights diverse intra- and extracellular mechanisms for the negative regulation of Nlgn2-mediated inhibitory synaptic function, indicating the critical role of Nlgn2 in chronic stress-induced neurological disorders." (PMID 39897557, 2025).
tumor (2 papers, 2021 to 2024). "Therefore, the comprehensive relationship between NLGN2 and immunological changes in the tumor microenvironment, as well as the mechanisms underlying mitochondrial involvement, remain to be elucidated by further gain or loss-of-function assays." (PMID 34804909, 2021). "In the 69 positive samples, NLGN2 exhibited different localization patterns in the patients, with minor differences within the same tumor." (PMID 38413734, 2024). "Moreover, the unusual positioning of NLGN2 in mitochondria was also observed in several other tumor and normal cell lines, including U2OS, U251MG and NIH3T3." (PMID 34804909, 2021). "NLGN2 was highly expressed in 75% (75/100) of the tumor samples, and its expression level was significantly associated with tumor size, lymph node metastasis, TNM stage and histological grade (all p < 0.05), but not with patient age or the expression levels of ER, PR and HER2 (all p > 0.05)." (PMID 34804909, 2021). "The relationship between NLGN2 expression and CD3+ and CD8+ tumor infiltrating lymphocytes." (PMID 34804909, 2021). "NLGN2 was identified as a favorable prognostic factor in the tumor lymph node non-metastatic (-) patients (HR, 0.65; 95%CI, 0.44 to 0.97; p < 0.05), but not in the tumor lymph node metastatic (+) patients (HR, 0.92; 95%CI, 0.72 to 1.19; p > 0.05)." (PMID 34804909, 2021).
NLGN2 also shares sentences with these, for which no sentence is quoted: autism spectrum disorder (4 papers); migraine (2); Obesity (2); adenocarcinoma (1); brain tumors (1); diabetic cardiomyopathy (1); Dyskinesia (1); genetic disorders (1); glioblastoma multiforme (1); glioma (1); hearing loss (1); mental disorder (1); pervasive developmental disorder (1); tauopathy (1).